NLRP3 (NLR family pyrin domain containing 3)
Diseases named in the same sentence as NLRP3 in open-access papers (continued):
Sharing a sentence is not in itself a finding about the gene and the disease.
kidney inflammation (32 papers, 2011 to 2026). "A possible explanation for this specific result is that existing strong evidence of NLRP3 inflammasome participation in kidney inflammation caused by kidney stones, which is closely related to neutrophils." (PMID 36294835, 2022). "We verified that NIBV induced kidney inflammation in chickens by activating pyroptosis through the MDA5/NF-κB/NLRP3 signalling pathway, providing new insights into the molecular regulatory mechanism of NIBV." (PMID 41327426, 2025). "Nephritis plays a dominant role in septic AKI, and activation of the nucleotide oligomerization domain-like receptor protein 3 (NLRP3) inflammasome is critical for the development of nephritis." (PMID 37396949, 2023). "It has also been shown that m6A modification of PPAR-α activates NLRP3 inflammasomes and NF-κB-driven kidney inflammation." (PMID 35656115, 2022). "This indicates that PSCP can prevent kidney inflammation by inhibiting the activation of the NLRP3 inflammasome." (PMID 35223948, 2022). "When the NLRP3 inflammasome is activated, the secretion of proinflammatory cytokines IL-18 and IL-1β is increased, with kidney inflammation and fibrosis being amplified." (PMID 34504642, 2021). "IL-1β, a pro-inflammatory mediator known to have systemic consequences, is a marker of NLRP3 inflammasome activation and can promote kidney inflammation." (PMID 34680443, 2021). "An increasing amount of evidence indicates that high urate level directly activates the NLRP3 inflammasome and subsequently promotes IL-1β maturation and secretion, contributing to kidney inflammation and renal dysfunction." (PMID 33959014, 2021). "The release of pro-inflammatory cytokines is the key of kidney inflammation, and NLRP3 inflammatory pathway plays a crucial role in regulating inflammation." (PMID 33959014, 2021). "The experimental results showed that continuous DOS administration for 8 weeks effectively inhibited kidney inflammation, inhibited renal lesions, and maintained normal renal UA transport and excretion by inhibiting renal NLRP3 inflammasome expression." (PMID 32308702, 2020). "The capacity of quercetin to regulate the NLRP3 inflammasome has also been reported, given its capacity to ameliorate kidney inflammation by blocking NLRP3 inflammasome activation and impairing caspase-1 and IL-1β expression." (PMID 32650482, 2020). "In summary, heterologous anti-GBM nephritis develops independently of the NLRP3-ASC-caspase-1 axis likely due to an inability for glomerular cells to induce and to secrete IL-1β." (PMID 22046355, 2011). "However, the role of the MDA5/NF-κB/NLRP3 innate immune signalling pathway in NIBV-induced kidney inflammation is unclear." (PMID 41327426, 2025). "Thus, heme also seems to be a potentially dangerous activator of the NLRP3 inflammasome, which actually plays a key role in IL-1β secretion during experimental kidney inflammation." (PMID 31346322, 2019). "Direct evidence comes from LPS-enhanced heterologous anti-GBM nephritis in rats which were found to be partially protected by anti-IL-1β antibody treatment, but a contribution of NLRP3, ASC, and caspase-1 for intrinsic glomerular inflammation is still speculative." (PMID 22046355, 2011). "Concurrently, it inhibited the mRNA expression of renal inflammatory cytokines via the inhibition of NLRP3/Caspase-1 and TLR4/MyD88/NF-κB signaling pathways, thereby alleviating the HUA-induced kidney inflammation." (PMID 41300001, 2025). "Accumulating evidence suggests that the limitation of the NLRP3 inflammasome and JAK2/STAT3 signaling contributes to attenuate kidney inflammation." (PMID 41278550, 2025). "Emerging evidence has indicated that the NLRP3 inflammasome plays a crucial role in the progression of HUA and kidney inflammation." (PMID 36438835, 2022).
kidney inflammation (continued). "Accumulating studies have shown that the NLRP3 inflammasome, which is composed of the NLRP3 protein, caspase-1, and ASC, plays a pivotal role in DKD kidney inflammation, especially in podocytes, endothelial cells, and renal tubular epithelial cells." (PMID 34504642, 2021). "To determine the role of NLRP3, ASC, and caspase-1 in glomerulonephritis, we induced heterologous anti-GBM nephritis in mice with targeted deletions of Nlrp3, Asc, and caspase-1." (PMID 22046355, 2011). "Inhibition of caspase-1 or NLRP3-mediated inflammasome signaling in murine models has demonstrated that inflammasome pathways contribute to SLE pathogenesis by promoting autoantibody production, endothelial dysfunction, and nephritis." (PMID 35664004, 2022). "The NLRP3 inflammasome is involved in erythema, nephritis, NP-SLE, and other organ damage, so inhibition of the NLRP3 inflammasome may have surprising effects." (PMID 35664004, 2022). "NLRP3 (NOD-like receptor family pyrin domain containing 3) inflammasome, suggesting inflammation may be present, plays a vital role in the pathogenesis of kidney inflammation." (PMID 34819865, 2021). "The intrarenal expression of NLRP3, ASC, and caspase-1 suggests that they might be involved in the secretion of IL-1β and inflammation during anti-GBM nephritis." (PMID 22046355, 2011).
periodontal disease (32 papers, 2015 to 2025). "Specific genetic polymorphism in NLRP3 (T/C genotype) are associated with periodontal disease susceptibility." (PMID 38817019, 2024). "Infection with these bacteria activates the NLRP3 inflammasome, indicating that the NLRP3 inflammasome is associated with the pathogenesis of periodontal disease." (PMID 35628185, 2022). "Furthermore, the positive association between CAL and rs10925024 NLRP3 polymorphisms suggested a possible role in increasing the severity of periodontal disease." (PMID 36812929, 2023). "The authors concluded that synergistic interaction of the CT/CC genotypes of NLRP3 (rs4612666) SNP with ageing and smoking habits might potentially undermine the pathogenic tract of periodontal disease." (PMID 36429405, 2022). "Furthermore, periodontal disease is considered to be a risk factor for other NLRP3 inflammasome-related diseases, such as RA, diabetes, and Alzheimer’s disease." (PMID 35628185, 2022). "In addition to the signals provided by a pathogen for NLRP3 activation, the polymorphism related to higher transcriptional activation of the NLRP3 gene should be considered as a risk factor in the pathogenesis of periodontal disease." (PMID 38817019, 2024). "This interplay highlights the potential of targeting NLRP3 and enhancing IL-37 as a therapeutic approach for the treatment of periodontal disease." (PMID 40267956, 2025). "Suppression of Zn/Cu SOD expression in inflammatory periodontal diseases increases the production of inflammasome components of the NOD-like receptor protein 3 (NLRP3) inflammasome." (PMID 40136440, 2025). "An overexpression of the NLRP3 inflammasome and a downregulation of NLRP3 inhibitors have been observed in the gingival tissue of patients with periodontal disease." (PMID 38817019, 2024). "Studies performed on gingival tissue have shown that NLRP3 expression was significantly higher in different types of periodontal diseases as compared to healthy individuals." (PMID 38817019, 2024). "Many advances in the field knowledge show that the NLRP3 inflammasome activity stimulated by periodontal microbiota drive periodontal disease pathogenesis and progression." (PMID 38817019, 2024). "A narrative review was conducted in order to depict the current knowledge on the relationship between NLRP3 inflammasome activity and periodontal disease." (PMID 38817019, 2024). "The review provides new insights into the relationship between the NLRP3 inflammasome activity and periodontal disease pathogenesis, highlighting the roles and regulatory mechanism of inflammatory molecules involved in the disease process." (PMID 38817019, 2024). "The NLRP3 inflammasome activity stimulated by periodontal microbiota drive periodontal disease pathogenesis and progression." (PMID 38817019, 2024). "In inflammatory pathologies, such as periodontal diseases, the responsible pathogens can trigger pyroptosis of host cells through NLRP3 activation." (PMID 39679199, 2024). "Clinical studies have evaluated NLRP3 inflammasome expression in periodontal disease, using tissue, saliva and/or gingival crevicular fluid (GCF) samples." (PMID 38817019, 2024). "Taken together, these studies support that the NLRP3 inflammasome is involved in the pathogenesis of periodontal disease." (PMID 35628185, 2022). "The current study also pointed to Galcectin-3, NLRP3, IL-1b as an additional biomarker in crevicular fluid, which controls the progress of periodontal disease." (PMID 34829603, 2021). "We also performed real-time RT-PCR to detect FimA and NLRP3 gene expression in gingival samples from diabetic patients with periodontal disease." (PMID 28083517, 2016). "These images show that the intensity and area of SREBP-1c and NLRP3 increased in diabetic patients with periodontal disease compared to patients with periodontal disease alone." (PMID 28083517, 2016).
periodontal disease (continued). "Since it is not possible to cover the field of rapidly growing inflammasome biology in a single review, the objective of this paper was to summarize key general concepts about NLRP3 inflammasome activation and regulation, and importantly, what is known so far of their role in periodontal disease." (PMID 38817019, 2024). "Thus, the abnormal activation or overexpression of NLRP3 in osteoclasts, osteoblasts, fibroblasts, and immune cells is considered to play a critical role in the pathogenesis of periodontal disease." (PMID 39679199, 2024). "In the future, targeting leptin/NLRP3 signaling may be applied to elucidate the mechanisms of the alveolar bone and periodontal diseases." (PMID 36979821, 2023). "The NLRP3 inflammasome and the following response from the IL-1 family might play an important role in periodontal disease triggered via P. gingivalis challenge through sustained inflammatory milieu." (PMID 36986299, 2023). "Indeed, a clinical study reported significantly higher expression of NLRP3 in gingival tissues of patients with periodontal disease compared with controls." (PMID 35628185, 2022). "Metformin, an oral antidiabetic drug, exhibits anti-inflammatory effects by reducing the activity of inflammasomes containing NLRP3, suggesting that anti-inflammatory drugs may be useful in the prevention and treatment of periodontal disease." (PMID 36163018, 2022). "The ROS/TXNIP/NLRP3 inflammasome signaling pathway may play an important role in the pathogenesis of periodontal disease." (PMID 35083332, 2022). "OSAHS may affect the incidence of periodontal diseases through the ROS/TXNIP/NLRP3 inflammasome signaling pathway." (PMID 35083332, 2022). "The NLRP3 inflammasome is responsible for regulating innate immune responses in chronic inflammatory diseases and NLRP3 inflammasome inhibition is a new target in the treatment of periodontal disease." (PMID 33806682, 2021). "Although a recent study suggested that PKR modulates inflammation by regulating the expression of the NLRP3 inflammasome through the NF-κB pathway in periodontal diseases, further studies are required to clarify the role of PKR in NLRP3 inflammasome activation." (PMID 34064909, 2021). "Chronic hepatitis C and periodontal disease could have a significant influence on the upregulation of NLRP3 inflammasome and its components, possibly contributing to an increased local inflammatory reaction and clinical periodontal consequences." (PMID 34840527, 2021). "The two-signal model of activation of NLRP3 was already demonstrated in the context of periodontal disease by stimulating primary gingival epithelial cells with Porphyromonas gingivalis, which resulted in downregulation of NLRP3 expression and increase of pro-interleukin-1β expression." (PMID 32385413, 2020). "Considering that bacterial LPS is a major disease-inducing antigen in periodontal diseases, we assessed the role of Nlrp3 and Caspase-1 on the expression of the inflammation- and macrophage phenotype-associated genes Il-10, Il-12 and Tnf-α in primary bone marrow-derived macrophages." (PMID 32385413, 2020). "Nucleotide-binding oligomerization domain (NOD)-like receptor (NLR) family pyrin domain containing 3 (NLRP3) inflammasome-mediated interleukin-1β (IL-1β) is significantly involved in periodontal diseases, and notably P. gingivalis enables to modulate the induction and expression of NLRP3." (PMID 32903638, 2020). "This inceptive study intends to contribute to bridge this gap of knowledge, by providing insights into the role NLRP3 inflammasome and of Caspase-1 on inflammation and alveolar bone resorption in a murine model of bacterial-induced experimental periodontal disease." (PMID 32385413, 2020). "Limited clinical studies have explored the presence of NLRP3 as it relates to periodontal disease." (PMID 31850638, 2020). "The attenuation of this periodontal disease may correlate with the regulation of AhR/NF-κB/NLRP3 inflammasome pathway by VD3." (PMID 31691738, 2019).
periodontal disease (continued). "NLRP3 inflammasome has also been reported to express in periodontal diseases." (PMID 27626170, 2016). "In addition, gingival tissues from diabetic patients with periodontal disease exhibited higher NLRP3 and SREBP-1c expression." (PMID 28083517, 2016). "Thus, the levels of NLRP3 in saliva have been proposed as markers of periodontal disease." (PMID 38256037, 2024). "Therefore, chronic inflammation and/or pathogens in periodontal disease might play a role in accelerating the development of these diseases through IL-1 and NLRP3 inflammasome activation." (PMID 35628185, 2022). "Bone resorption in Nlrp3-KO mice did not significantly change in comparison with WT mice, implying that caspase-1 is instrumental in modulating inflammation caused by bacteria of periodontal disease, and may be regulated by genes other than NLRP3." (PMID 33215255, 2021). "Third, when compared to patients with periodontal disease alone, the results of IHC staining also demonstrated that SREBP-1c and NLRP3 were increased in the gingival tissues of diabetic patients with periodontal disease." (PMID 28083517, 2016). "Thus, NLRP3 and CAS1, the hallmarks of pyroptosis signalling, are increasingly expressed in periodontal disease compared to healthy tissue." (PMID 35563469, 2022). "In summary, NLRP3 inflammasome did not play a significant role in inflammation and bone resorption in the heat-killed Aa-induced periodontal disease model; whereas lack of Caspase-1 attenuated inflammatory bone resorption and the infiltration of PMNs." (PMID 32385413, 2020). "Increased expression of NLRP3 and AIM2 in the gingival tissues of patients with periodontal disease is positively correlated with the levels of IL-1β and IL-18, suggesting that various inflammasomes may participate in the microbial-induced inflammation in periodontal diseases." (PMID 32385413, 2020). "As an inceptive study, these results suggest that Nlrp3 inflammasome does not play a significant role in inflammation and bone resorption in vivo and that Caspase-1 has a pro-resorptive role in experimental periodontal disease." (PMID 32385413, 2020). "In addition, these results indicate that other inflammatory pathways are involved in the pathogenesis of periodontal diseases, as inflammation and alveolar bone resorption were not completely abrogated in either Nlrp3- or Casp1-KO mice." (PMID 32385413, 2020).
acne (31 papers, 2008 to 2025). An inflammatory process of the sebaceous glands which is characterized by comedones, nodules, papules and/or pustules on the skin. "For instance, a study by Li and colleagues showed that ADSCs diminished IL-1β secretion by restricting mitochondrial ROS production, which further obstructed the NLRP3 inflammasome and alleviated inflammation linked to acne." (PMID 40422225, 2025). "The leading acne-associated bacterium, C. acnes, stimulates the immune system through NLRP3 activation." (PMID 41178942, 2025). "The activation of the NLRP3 inflammasome promotes the maturation of caspase-1 and triggers the release of the downstream acne-pathogenic cytokines IL-1β and IL-18, which subsequently activates the secondary inflammatory mediators, including IL-6 and IL-832." (PMID 38062074, 2023). "The NLRP3 inflammasome pathway is reportedly activated by P. acnes, which has been recently associated with the pathogenesis of acne." (PMID 36624865, 2022). "Among the multiple subtypes of family proteins, NLRP3 has been associated with acne; C. acnes activates this inflammasome inducing IL-1β production in a caspase-1 dependent manner involving potassium efflux." (PMID 35910763, 2022). "Based on these results, we selected compounds and evaluated whether compounds were able to inhibit the expression of NLRP3, IL-1β, 5α -R1 associated acne." (PMID 36624865, 2022). "They found that the rs10754558 polymorphism of NLRP3 gene is associated with acne susceptibility." (PMID 35328662, 2022). "Thus, the suppression of the NF-κB pathway and the activation of the ERK1/2 MAPK signal transduction pathways caused inhibition of caspase-1 and NLRP3 expression, which could be considered therapeutic targets in the treatment of acne." (PMID 36761775, 2023). "Moreover, genetic variants of NLRP3 could also be linked to acne vulgaris in a Han Chinese population." (PMID 33925158, 2021). "During acne pathogenesis, sebocytes and monocytes/macrophages can activate NLRP3 inflammasomes and release IL-1β." (PMID 41307843, 2025). "TLR2 has been shown to be highly expressed on perifollicular and peribulbar macrophages in acne lesions, and then in activation of the signaling cascade NLRP3 inflammasome, NF-kB and MAPK signalling pathways." (PMID 41010653, 2025). "C. acnes activates the NLRP3 inflammasome during acne development, resulting in a strong immune response." (PMID 38275656, 2024). "The NLRP3 inflammasome plays a key role in acne lesions, raising interest in the suppression of this mechanism in the treatment of acne." (PMID 36761775, 2023). "This response is evident as C. acnes induces the activation of monocyte-macrophage NLRP3-inflammasome and boosts the secretion of IL-1β in acne, thereby demonstrating its role in skin inflammation." (PMID 37344849, 2023). "First, C. acnes instigates a robust immune response that involves the NLRP3-inflammasome during acne development." (PMID 37344849, 2023). "This suggests that sebocytes are key immunocompetent cells and that C. acnes-induced NLRP3 activation in sebaceous glands plays a significant role in acne pathogenesis." (PMID 37344849, 2023). "It proves to be an effective inhibitor of NLRP3 inflammasome activity triggered by C. acnes, preventing the development of inflammation and exacerbation of acne lesions." (PMID 35889363, 2022). "This study indicates that anti‐acne therapy can potentially be developed by targeting the NLRP3 inflammasome." (PMID 35871079, 2022). "Licochalcone A and auranofin attenuate P. acnes-induced inflammation and acne symptoms through inactivation of NLRP3 inflammasome 38,39." (PMID 35414779, 2022). "It is worth noting that both NLRP3 active caspase-1 are expressed by tissue macrophages CD86+ in acne lesions, which also suggests the participation of inflammasome complexes in acne pathogenesis." (PMID 35329904, 2022). "The activation of NLRP3 indicated there were pathological changes related to acne in the THP-1 cells." (PMID 35871079, 2022).